COLEC11 (collectin subfamily member 11)
Diseases named in the same sentence as COLEC11 in open-access papers (continued):
Sharing a sentence is not in itself a finding about the gene and the disease.
infection (4 papers, 2015 to 2025). The state of being infected such as from the introduction of a foreign agent such as serum, vaccine, antigenic substance or organism. "We utilized a Nigerian study group consisting of 167 Schistosoma haematobium infected individuals and 186 matched healthy subjects, and investigated the contribution of CL-K1 deficiency and of COLEC11 polymorphisms to infection phenotype." (PMID 25807310, 2015). "In addition, the COLEC11*TCCA haplotype harboring the rs7567833-A polymorphism occurred more frequently in healthy controls compared to the infection group, suggesting that individuals with this haplotype were protected from S. haematobium infection." (PMID 25807310, 2015). "Here the analyzed COLEC11 genetic variant does not lead to protein deficiency, but it may alter protein function, being associated with the development of infection and pathophysiology of CD." (PMID 30995222, 2019). "The COLEC11 homozygous genotype of the major allele rs7567833-GG was observed significantly more often in the SEP group compared to SELN controls after adjusting for age and gender (OR = 2.35, 95%CI = 1.26–4.37,Pcorr = 0.004), suggesting an association with increased risk of infection." (PMID 25807310, 2015). "However, COL14A1, COLEC11, and COLEC12 were uniquely downregulated following Delta infection at 24 hpi." (PMID 41200555, 2025). "When the individuals with COLEC11*TCCA were analyzed for CL-K1 serum levels in the different patient groups, SEP individuals had lower levels than egg negatives, indicating that CL-K1 serum levels were modulated by infection." (PMID 25807310, 2015).
tumor (3 papers, 2023 to 2025). "The second set of experiments was performed in WT and Colec11–/– mice; the effect of L-Fucose treatment on tumor growth was assessed and compared in the 2 groups of mice." (PMID 36883567, 2023). "Furthermore, the staining of CD8 showed that, compared with WT mice, Colec11–/– mice exhibited markedly increased CD8+ infiltrates in the tumor core and tumor edge." (PMID 36883567, 2023). "Colec11–/– mice had significantly reduced tumor burden compared with WT mice." (PMID 36883567, 2023). "The tumor volume and weight were significantly reduced in Colec11–/– mice compared with WT mice." (PMID 36883567, 2023). "In particular, GGACT, LXN, THY1, SYNPO2, ACMSD and COLEC11 showed no survival or recurrence associations from the tumor data, suggesting these as unique biomarkers from NAT." (PMID 37575948, 2023). "Transcriptomically, PRELP+ CAFs exhibit a unique signature defined by extracellular matrix components (e.g., PRELP, COLEC11, ITGBL1) and the activation of pro-tumor pathways such as TGF-β and Wnt signaling." (PMID 41031085, 2025). "Flow cytometry analysis showed that the percentage of tumor-infiltrating CD45+ cells was comparable between WT and Colec11–/– mice." (PMID 36883567, 2023). "Using our dataset and another high-quality dataset, we identified proteins that showed clinical prognosis and recurrence associations, of which GGACT, LXN, THY1, SYNPO2, ACMSD and COLEC11 were unique biomarkers identified from NAT that could not be revealed using tumor-based analysis." (PMID 37575948, 2023). "The costaining of CD3 and CD11b or CD3 and F4/80 showed that, compared with WT mice, Colec11–/– mice exhibited clearly more CD3+ infiltrates and much less CD11b+ and F4/80+ infiltrates in the tumor core and in the outskirt of the tumors." (PMID 36883567, 2023).
heart disease (1 paper, 2024). "While complement inhibitors have been suggested as a potential therapeutic target for heart disease, more studies on the relationship between COLEC11 and CAD are warranted." (PMID 39025905, 2024).
COLEC11 also shares sentences with these, for which no sentence is quoted: kidney disease (3 papers); diabetes (2); lung carcinoma (2); 3M syndrome (1); adenocarcinoma (1); age-related macular degeneration (1); ameloblastoma (1); Arthritis (1); Bloom syndrome (1); cancers of the salivary gland (1); Carnevale Syndrome (1); Cohen syndrome (1); complement deficiencies (1); coronary heart disease (1); COVID-19 (1); craniosynostosis (1); diabetic nephropathy (1); diarrheal disease (1); Disseminated intravascular coagulation (1); FILS syndrome (1); genetic disorder (1); ICF syndrome (1); infectious disease (1); inflammatory bowel disease (1); ischemia (1); ischemic stroke (1); Kabuki syndrome (1); kidney injury (1); lupus glomerulonephritis (1); malaria (1).
A further 10 diseases each share a sentence with COLEC11 in 1 paper.